RNU1-80P (RNA, U1 small nuclear 80, pseudogene)
Gene: Small nuclear RNA gene on chromosome 17 (77,920,098 to 77,920,258, forward strand). Ensembl gene ENSG00000238898.
Homologues: Orthologues: chimpanzee U1 (96% identical), macaque U1 (89% identical). Paralogues in human: RNU1-11P (85% identical), RNU1-89P (85% identical), RNU1-1 (84% identical), RNU1-2 (84% identical), RNU1-27P (84% identical), RNU1-28P (84% identical), RNU1-3 (84% identical), RNU1-4 (84% identical), RNVU1-18 (84% identical), RNVU1-29 (84% identical), U1 (84% identical), RNVU1-28 (84% identical), and 134 more.